SUV39H1 (SUV39H1 histone lysine methyltransferase)
Diseases named in the same sentence as SUV39H1 in open-access papers (continued):
Sharing a sentence is not in itself a finding about the gene and the disease.
squamous cell carcinoma (2 papers, 2013 to 2024). A carcinoma arising from squamous epithelial cells. "Although SUV39H1 was significantly upregulated in adenocarcinoma and squamous cell carcinoma tissue samples in our microarray analysis, supporting its positive role in tumorigenesis, it was found to be downregulated in blood samples in our qPCR validation." (PMID 24564251, 2013). "After analysis, it was found that the expression of SUV39H1 in squamous cell carcinoma at T1+T2 was significantly lower than that in squamous cell carcinoma at T3+T4, suggesting that SUV39H1 may play an important regulatory role in the progression of OSCC." (PMID 38650654, 2024). "Frozen NSCLC tissue-based microarray analysis revealed that E2F6, TFDP1, SUV39H1, and HMGA1 are significantly upregulated in both the adenocarcinoma and squamous cell carcinoma samples." (PMID 24564251, 2013). "We found that E2F6, HMGA1, IRF1, and TFDP1 were upregulated and RBL1, SUV39H1, and HNRPD were downregulated or aberrantly expressed in adenocarcinoma and squamous cell carcinoma, which are the sub-types of NSCLC." (PMID 24564251, 2013). "Therefore, combining the microarray and qPCR results, upregulation of E2F6, HMGA1, IRF1, and TFDP1 and downregulation or no expression of SUV39H1, RBL1, HNRPD can be used as diagnostic markers of NSCLC, and, in particular, adenocarcinoma and squamous cell carcinoma." (PMID 24564251, 2013).
Stroke (2 papers, 2021 to 2022). Sudden impairment of blood flow to a part of the brain due to occlusion or rupture of an artery to the brain. "Furthermore, NR_045414 (ASHGV40037155) at 4p16.3 mapped within 8 kb of HTT and is associated with post-stroke depression (PSD), while ENST00000416061 (ASHGV40053990)’s genomic coordinates were 3.4 kb downstream of SUV39H1, a histone methyltransferase related to stroke." (PMID 35754821, 2022).
thyroid cancer (2 papers, 2024 to 2025). "However, SUV39H1 transcription is reduced in thyroid cancer (THCA)." (PMID 38650654, 2024).
acute liver failure (1 paper, 2026). Rapid deterioration of liver function causing encephalopathy and coagulopathy. "Finally, a significant correlation between Suv39h1, HMGB2 and proliferative markers was identified in patients with acute liver failure." (PMID 41963467, 2026).
astrocytic tumor (1 paper, 2015). A glial tumor of the brain or spinal cord showing astrocytic differentiation. "A novel finding is that H3K9me3 levels increased in parallel with those of SETDB1 consistent with the notion that this histone mark is preferentially established by SETDB1 rather than by SUV39H1 in astrocytic tumors." (PMID 25602259, 2015).
autoimmune disease (1 paper, 2022). A disorder resulting from loss of function or tissue destruction of an organ or multiple organs, arising from humoral or cellular immune responses of the individual to their own tissue constituents. "Knockdown of SUV39H1 partially blocked TGF-β-mediated IL-2 inhibition; thus, SUV39H1 may become a new target for autoimmune disease therapy." (PMID 35965506, 2022).
B-cell acute lymphoblastic leukemia (1 paper, 2024). A neoplasm of lymphoblasts committed to the B-cell lineage, typically composed of small to medium-sized blast cells. "Then, in order to further explore whether SUV39H1 knockout could improve the tumoricidal capacity of CAR‐T cells, SUV39H1‐disrupted, CAR‐transduced T cells and unedited CAR‐T cells were respectively infused into B cell acute lymphoblastic leukemia mouse models to compare the difference in efficacy." (PMID 38645666, 2024).
Cognitive impairment (1 paper, 2022). Abnormal cognition is characterized by deficits in thinking, reasoning, or remembering. "Changes in the BDNF expression have been shown to inversely correspond to increased H3K9me3 in a postoperative model of cognitive impairment or downregulation in mice with inhibited activity of SUV39H1." (PMID 35042834, 2022).
colorectal tumours (1 paper, 2006). "Colorectal cell lines showed SIRT1, EZH2, PCAF underexpression and SUV39H1 overexpression compared to colorectal tumours." (PMID 16638127, 2006).
Ewing sarcoma (1 paper, 2013). A small round cell tumor that lacks morphologic, immunohistochemical, and electron microscopic evidence of neuroectodermal differentiation. "Even at these lower concentrations, it significantly reduced the expression of BCL11B, and so prevented us from drawing any conclusions about the involvement of SUV39H1 in BCL11B mediated repression in Ewing sarcoma." (PMID 23527175, 2013). "We tested the necessity of these three co-repressors in BCL11B-mediated repression in Ewing sarcoma cells by shRNA knock-down for chomodomain helicase DNA binding protein 4 (CHD4), the core component of the NuRD complex, or chemical inhibitors targeting SUV39H1 or SIRT1." (PMID 23527175, 2013).
Fanconi anemia (1 paper, 2018). Fanconi anemia (FA) is a hereditary DNA repair disorder characterized by progressive pancytopenia with bone marrow failure, variable congenital malformations and predisposition to develop hematological or solid tumors. "FANCD2 protein belongs to the Fanconi Anemia Pathway and is required for repair of DSB and intra-S-phase checkpoint activation, while SUV39H1 is a methyltransferase that directs H3K9 methylation on large chromatin domains adjacent to the DSB to promote activation of DSB-signaling proteins." (PMID 30038706, 2018).
HIV-1 infection (1 paper, 2020). The type species of lentivirus and the etiologic agent of acquired immunodeficiency syndrome (AIDS). "The additional knockdown of SUV39H1 further reduced RBMX-mediated enhancement for HIV-1 infection from 6.1-fold to 2.6-fold, representing a 57% suppression." (PMID 32317327, 2020).
Infertility (1 paper, 2014). "The decrease in progeny viability for the ΔEZL3 cells missing H3K23me3 is also similar in scope to reported infertility and increased spermatocyte apoptosis in male mice missing both copies of the H3K9me3 methyltransferases, Suv39h1/2." (PMID 25161194, 2014).
Insulin resistance (1 paper, 2018). Increased resistance towards insulin, that is, diminished effectiveness of insulin in reducing blood glucose levels. "In addition to Sirtuins, there are other epigenetic modification enzymes, including SUV39H1 and EZH2 are involved in insulin resistance and T2DM." (PMID 30574122, 2018).
kidney stone (1 paper, 2025). "Additionally, the findings of the CIBERSORT investigation indicated that FZD7 and SUV39H1 may be linked to variations in the immune milieu of people who have kidney stones." (PMID 40171220, 2025). "Among these, the expression of SUV39H1 and LCN2 was higher in the kidney stone model than in normal samples (p < 0.001), but the expression of FZD7 and STK11 was lower in the kidney stone model (p < 0.001)." (PMID 40171220, 2025). "Consistent with in vitro results, the expression of SUV39H1 and LCN2 was higher and the expression of FZD7 and STK11 was lower in the kidney stone model than in normal samples (p < 0.001)." (PMID 40171220, 2025).
metastatic colorectal cancer (1 paper, 2025). "SUV39H1 deposits H3K9me3 at the promoter of the cell death receptor–encoding FAS gene, repressing expression and inhibiting apoptosis in metastatic colorectal cancer cells." (PMID 40059829, 2025).
oral cancer (1 paper, 2023). "In oral cancer, nuclear SUV39H1 expression has been correlated with tumor stage and progression." (PMID 37887281, 2023).
osteosarcoma (1 paper, 2019). A usually aggressive malignant bone-forming mesenchymal neoplasm, predominantly affecting adolescents and young adults. "To further confirm these results, we used IFI16 CRISPR knockout (KO) osteosarcoma U2OS cells (U2OS 67) generated in our earlier studies to study the effect of IFI16 KO and re-introduction of IFI16 in a KO background on the recruitment of H3K9me3, SUV39H1 and GLP." (PMID 31682228, 2019).
pancreatic cancer (1 paper, 2017). "In pancreatic cancer, NFATc2 binding to p15 promoter recruits histone methyltransferase Suv39H1 resulting in H3K9 trimethylation, which allows docking of CBX3 to the repressor complex giving rise to p15 silencing." (PMID 28193906, 2017).
triple-negative breast carcinoma (1 paper, 2018). An invasive breast carcinoma which is negative for expression of estrogen receptor (ER), progesterone receptor (PR), and human epidermal growth factor receptor 2 (HER2). "It was recently shown that mTOR inhibitors impair homologous recombination repair and synergize with PARP inhibitors through a negative regulation of SUV39H1 in BRCA-proficient triple-negative breast cancer cell lines." (PMID 30038706, 2018).
Werner syndrome (1 paper, 2025). "Likewise, lamin A (LMNA) deficiency and the depletion of the DNA repair gene WRN, which occurs in Werner Syndrome (WS) and causes premature aging, leads to H3, SETDB1, SUV39H1 and HP1 deregulation, contributing to heterochromatin loss and DNA damage." (PMID 40886198, 2025).
cancer (76 papers, 2006 to 2025). A tumor composed of atypical neoplastic, often pleomorphic cells that invade other tissues. "This was particularly evident for NSCLC patients, a subgroup of which also showed lower SUV39H1 protein levels in cancer samples with relatively higher TRIP12 that was associated with a favorable prognosis." (PMID 41125851, 2025). "Their prognostic significance varies across cancer types, with SUV39H1 expression showing context-dependent risk, while SUV39H2 high expression typically indicates an unfavorable prognosis." (PMID 40849299, 2025). "Suv39H1 is a protein lysine methyltransferase that is implicated in several cancers, including NSCLC, and is also involved in EMT." (PMID 38424632, 2024). "As inhibition of Suv39h1 reverses T cell dysfunction and causes tumor rejection, Suv39h1 represents an actionable “epigenetic checkpoint” for T cell functions in cancer." (PMID 35768432, 2022). "Both SUV39H1 and SUV39H2 are prognostic markers for different cancers, but dependent on the tumor type, either a high or low expression of SUV39H1 constitutes a risk, while a high expression of SUV39H2 is unfavorable in most cases." (PMID 34357075, 2021). "The H3K9me3 is formed by a family of histone methyltransferases including SUV39H1, that have been recently described to be associated with cancer." (PMID 26840455, 2016). "Sp1, a cell growth and survival transcription factor, has been shown to associate with SUV39H1 upon hydrogen peroxide treatment in an epithelial carcinoma cell line, leading to growth arrest through the silencing of Sp1 target genes, including cyclin B1." (PMID 23705022, 2013). "In the double knockout Suv39h1/Suv39h2 mouse the reduced level of H3 K9 methylation is associated with genomeinstability and predisposition to cancer." (PMID 16638127, 2006). "A combination therapy targeting the proteins mediating these epigenetic aberrations, such as G9a/GLP or SUV39h1/h2, may be worth exploring for its potential to reduce resistance to chemotherapy and cancer relapse risk." (PMID 37414849, 2023). "Overexpression of SUV39H1 is known to be associated with cell proliferation in cancer." (PMID 31335867, 2019). "Suv39h proteins are preferentially targeted to the pericentric heterochromatin, and mice lacking both Suv39h1 and Suv39h2 show chromosomal instabilities and increased risk of cancer, associated with H3K9me loss." (PMID 24550937, 2014). "Elevated H3K9me3 levels have two implications in cancer: an increase in H3K9me3 levels in specific promoters is strongly associated with the suppression of tumor suppressor gene expression, and therefore inhibition of SUV39H1 or SETDB1 has been proposed as a promising therapeutic strategy in HCC." (PMID 40175344, 2025). "We next explored the relationship between TRIP12 and SUV39H1 protein levels in various cancer types." (PMID 41125851, 2025). "Our previous study revealed that SUV39H1 signaling contributes to the maintenance of repetitive elements and genomic stability across various cancer cell types." (PMID 40059829, 2025). "Next, we evaluated the translational potential of pharmaceutical targeting SUV39H1 with a small-molecule inhibitor F5446 that has previously been used in cancer research." (PMID 39603205, 2024). "Recently, two back‐to‐back studies were disseminated in Cancer Discovery, uncovering that the genetic ablation of SUV39H1 epigenetically augmented chimeric antigen receptor‐T (CAR‐T) cell function against solid tumors." (PMID 38645666, 2024). "Mechanistically, lower FBO44/SUV39H1 expression resulted in cancer cell death due to the induction of viral mimicry pathways stemming from RE de-repression, the presence of cytosolic dsRNA and dsDNA, and replication stress evoked by double-strand DNA breaks." (PMID 39519018, 2024). "MiR-130a-3p modulated the metastatic spreading of the carcinoma via Suv39H1/AKT/mTOR axis and sponging of the non-coding RNA by HOTAIR upregulated Suv39H1 responses, promoting cancer cell growth and metastasis." (PMID 40176927, 2024).
cancer (continued). "In GBM, SUV39H1 has been shown to have altered expression, and its activity can affect crucial pathways in cancer cell growth and therapy response." (PMID 39765675, 2024). "Inhibition of SUV39H1 in different types of cancer also stimulates interferon signaling, enhances cancer cell immunogenicity, reduces the expression of inhibitory receptors, and generally improves the efficacy of T-cell therapy." (PMID 39519018, 2024). "Genetic knockout or pharmacological inhibition of SUV39H1 in cancer cells/T cells potentiated immune checkpoint inhibitor (ICI) therapy." (PMID 38645666, 2024). "In cancer, SUV39H1 is often overexpressed, leading to increased H3K9 trimethylation and the consequent silencing of tumor suppressor genes, which promotes tumor progression in cancers such as prostate, breast, colon, lung, and DMG." (PMID 39765675, 2024). "In summary, the published reports indicate that SUV39H1/2 are promising targets for cancer treatment." (PMID 39519018, 2024). "As a histone methyltransferase, suppressor of variegation 3–9 homolog 1 (SUV39H1) plays an important role in the occurrence and development of cancer." (PMID 38017386, 2023). "SUV39H1 acts as a tumor suppressor in cervical cancer, parathyroid cancer and leukemia, but plays a cancer-promoting role in colorectal cancer and melanoma." (PMID 38017386, 2023). "In cancer studies, miR-520a has been associated with suppression of oncogenic signaling pathways including CDK4, SUV39H1, LIMK1, GOT-2, AKT1/mTOR, and PI3K/AKT31–37." (PMID 35149732, 2022). "FBXO44 recruits SUV39H1 to REs, which is essential for H3K9me3-mediated transcriptional silencing of REs in cancer cells." (PMID 34385592, 2022). "TCGA indicated that HOTAIR and Suv39H1 were highly expressed in the patients with different cancer subclasses/different nodal metastasis status/individual cancer stages (p < 0.05, vs Normal breast tissues by ANOVA)." (PMID 35619625, 2022). "Suv39H1 promotes tumor growth in human carcinoma, and pharmacological suppression of Suv39H1 is an effective approach to inhibit human carcinoma." (PMID 35619625, 2022). "Altogether, these findings suggested that cancer cell-derived EV-encapsulated miR-744 reduced the development of NSCLC by targeting SUV39H1." (PMID 33472665, 2021). "Our data also demonstrated that miR-744 shuttled by NSCLC cell-derived EVs arrested the proliferation of cancer cells by inhibiting SUV39H1 expression." (PMID 33472665, 2021). "Functional targeting of FBXO44/SUV39H1 induced DNA replication stress and viral mimicry selectively in cancer cells, leading to inhibition of tumor growth and enhanced anti-PD-1 therapy response in preclinical mouse models." (PMID 33681705, 2021). "A previous study has demonstrated that upregulated SUV39H1 facilitates cancer cell proliferation, enhances migratory potency of cancer cells, and suppresses cancer cell apoptosis." (PMID 33472665, 2021). "By using co-IP assays, we found that endogenous Dicer interacts with endogenous SUV39H1 in human cancer cells." (PMID 34705508, 2021). "NV10, a small molecule inhibitor of SUV39H1, exhibited anti-cancer activity in vivo and in vitro in several cancers." (PMID 28505071, 2017). "According to the Khan Multi-cancer study, SUV39H1 expression is down in RMS, including both ERMS and ARMS subtypes, compared to skeletal muscle tissue samples." (PMID 23705022, 2013). "The current study demonstrates that expression of SUV39H1 and G9a is important to support the growth of malignant cells, although they play distinct roles in cancer cells." (PMID 18446223, 2008). "Further studies need to address the mechanistic links between G9a, SUV39H1 and chromosomal/telomere structures as well as hTERT expression in cancer cells." (PMID 18446223, 2008). "Here, we show that knockdown (KD) of G9a and SUV39H1 in cancer cells remarkably inhibited cell growth and led to morphologically senescent cells with telomere abnormalities." (PMID 18446223, 2008).